IGKV1-5 (immunoglobulin kappa variable 1-5)
Description:
V region of the variable domain of immunoglobulin light chains that participates in the antigen recognition. Immunoglobulins, also known as antibodies, are membrane-bound or secreted glycoproteins produced by B lymphocytes. In the recognition phase of humoral immunity, the membrane-bound immunoglobulins serve as receptors which, upon binding of a specific antigen, trigger the clonal expansion and differentiation of B lymphocytes into immunoglobulins-secreting plasma cells. Secreted immunoglobulins mediate the effector phase of humoral immunity, which results in the elimination of bound antigens. The antigen binding site is formed by the variable domain of one heavy chain, together with that of its associated light chain. Thus, each immunoglobulin has two antigen binding sites with remarkable affinity for a particular antigen. The variable domains are assembled by a process called V-(D)-J rearrangement and can then be subjected to somatic hypermutations which, after exposure to antigen and selection, allow affinity maturation for a particular antigen.
Synonyms: IGKV; IGKV15; L12; L12a; V1
Tractability: Antibody: its Gene Ontology location is reachable by antibodies, with high confidence; UniProt places it where antibodies can reach, with medium confidence; UniProt predicts a signal peptide or a membrane-spanning region.
Gene: Immunoglobulin variable (V) gene on chromosome 2 (88,947,301 to 88,947,957, reverse strand). Ensembl gene ENSG00000243466.
Subcellular location: Secreted; Cell membrane
Pathways (Reactome):
Immune System: Antigen activates B Cell Receptor (BCR) leading to generation of second messengers; CD22 mediated BCR regulation; Classical antibody-mediated complement activation; FCERI mediated Ca+2 mobilization; FCERI mediated MAPK activation; FCERI mediated NF-kB activation; FCGR activation; Fc epsilon receptor (FCERI) signaling; Immunoregulatory interactions between a Lymphoid and a non-Lymphoid cell; Initial triggering of complement; Regulation of Complement cascade; Regulation of actin dynamics for phagocytic cup formation; Role of LAT2/NTAL/LAB on calcium mobilization; Role of phospholipids in phagocytosis
Disease: FCGR3A-mediated IL10 synthesis; FCGR3A-mediated phagocytosis; Potential therapeutics for SARS
Hemostasis: Cell surface interactions at the vascular wall
Vesicle-mediated transport: Scavenging of heme from plasma
Gene Ontology:
Molecular function: antigen binding
Biological process: immune response
Cellular component: blood microparticle; extracellular exosome; extracellular region; immunoglobulin complex; plasma membrane
Homologues: Orthologues: macaque IGKV1-5 (74% identical), mouse Igkv15-103 (74% identical). Paralogues in human: IGKV1-9 (91% identical), IGKV1D-13 (91% identical), IGKV1-12 (89% identical), IGKV1-39 (89% identical), IGKV1D-16 (89% identical), IGKV1D-39 (89% identical), IGKV1D-12 (88% identical), IGKV1-17 (87% identical), IGKV1-16 (86% identical), IGKV1-27 (85% identical), IGKV1-6 (85% identical), IGKV1D-17 (85% identical), and 81 more.
Diseases named in the same sentence as IGKV1-5 in open-access papers:
IGKV1-5 is named in the same sentence as 4 diseases in open-access papers, as found by Europe PMC text mining. Sharing a sentence is not in itself a finding about the gene and the disease. The quoted sentences say what the papers report.
acute myeloid leukemia (2 papers, 2015 to 2025). Acute myeloid leukemia (AML) is a group of neoplasms arising from precursor cells committed to the myeloid cell-line differentiation. "In hematologic cancers like acute myeloid leukemia (AML), the IGKV1-5/IGKJ3*01 rearrangement in myeloblasts upregulates fLMP and CXCL12, chemotactic factors that drive AML cell migration and dissemination." (PMID 40806736, 2025).
acute leukemia (1 paper, 2025). A clonal (malignant) hematopoietic disorder with an acute onset, affecting the bone marrow and the peripheral blood. "The results of our study suggest that the increased expression of ACTB and the molecular interplays involving “HBA1&HBB," “HBB&HBA1," “IGKV1-5&IGHV4-31," “IGHV4-31&IGKV1-5," “HLA-DRA&CD74" and “ACTB&ACTB" might contribute to the progression of acute leukemia." (PMID 40338916, 2025). "Furthermore, the suppression of ACTB and the molecular interactions involving pairs such as “HBA1&HBB", ”HBB&HBA1", “IGKV1-5&IGHV4-31", “IGHV4-31&IGKV1-5", “HLA-DRA&CD74", and “A CTB&ACTB" might provide essential insights into unraveling the intricate mechanisms of acute leukemia." (PMID 40338916, 2025).
glioma (1 paper, 2021). A benign or malignant brain and spinal cord tumor that arises from glial cells (astrocytes, oligodendrocytes, ependymal cells). "In glioma grade III, highly activated DEGs included CFAP45, PLBD1, RASSF9, IGKV3-11, IGKV1-5, and NTS, while highly downregulated DEGs included NPAS4 and LINC01007." (PMID 33948562, 2021).
IGKV1-5 also shares sentences with these, for which no sentence is quoted: adenoma (1 paper).